SREBF1 (sterol regulatory element binding transcription factor 1)
Diseases named in the same sentence as SREBF1 in open-access papers (continued):
Sharing a sentence is not in itself a finding about the gene and the disease.
steatosis (284 papers, 2007 to 2026). Increased lipid within the cytoplasm of cells. "BPA caused mild steatosis in normal-diet mice through upregulated lipogenesis (Srebf1, Scd1) and ER stress genes." (PMID 40475995, 2025). "In contrast, HFD+CHOL caused macrovesicular steatosis, inflammation, early fibrosis, atherogenic dyslipidemia, intrahepatic cholesterol accumulation, hepatocyte apoptosis, upregulated Srebf1, Cyp7a1, and Nfkb1 expression, and activated Nrf2-dependent antioxidant responses." (PMID 42196216, 2026). "In addition, the livers of NprcAKO mice were essentially devoid of steatosis, which was associated with reduced expression of lipogenic and fatty acid uptake genes (such as Lpl, Acca, and Srebf1)." (PMID 28743802, 2017). "The important role of Srebf1 in lipogenesis is confirmed by studies indicating that the expression of this gene in the livers of patients with non-alcoholic steatosis is significantly higher than in healthy individuals." (PMID 40868056, 2025). "To confirm the role of SREBP-1c in ZFD-induced lipogenesis and steatosis, we treated ZFD-fed CONVR mice with Srebf1-specific antisense oligonucleotides (ASO) for three weeks, causing a reduction of hepatic Srebf1 expression by 70%." (PMID 40345386, 2025). "The impaired regulation of key pathways, such as reduced SREBF1-driven lipogenesis and altered cholesterol/bile acid homeostasis, could promote hepatocellular injury and fibrogenesis, increasing the risk of progression from simple steatosis to steatohepatitis and advanced liver disease." (PMID 40700094, 2025). "In OVX CBPA, BPA induced mild steatosis, increasing hepatic lipids and lipogenic/ER stress gene (Srebf1, Scd1, Hspa5, Atf6) expression." (PMID 40475995, 2025). "Both uroguanylin and guanylin downregulated basal and palmitate-induced transcription of Srebf1 and Dgat1 as well as steatosis in RIN-5mF β-cells (all P<0.05)." (PMID 37274331, 2023). "Evidence showed that steatosis that developed in rats fed a HFD diet resulted from activation of SREBF-1 and oxidative stress." (PMID 34441564, 2021). "Acknowledging these caveats, one plausibly direct mechanism for the increased steatosis observed in the livers of HFD-fed NCoRω-/- mice involves increased activity of LXRα resulting in increased expression of Srebf1." (PMID 33104749, 2020). "SREBF1 target genes, which are also involved in de novo lipid synthesis and steatosis development, were slightly upregulated in IGF2 overexpressing mice supporting lipogenic actions of IGF2." (PMID 27199763, 2016). "There was also a significant down-regulation of Abcb1a, an additional marker for cholestasis, as well as Srebf1, indicative of steatosis." (PMID 27598887, 2016). "Moreover, the upregulation of SREBF1, out of 10 steatosis-related genes suggests a steatotic effect of CV." (PMID 38992651, 2024). "Importantly, both guanylin and uroguanylin decreased basal and palmitate-induced steatosis and downregulated factors involved in lipogenesis (Srebf1, Mogat2 and Dgat1)." (PMID 37274331, 2023). "By contrast, at least a part of the steatosis observed in the HFD control group may be due to increased de novo lipogenesis because SREBF1 is significantly activated, and insulin, the transcriptional inducer of Srebp1c, is elevated." (PMID 34444996, 2021). "In models of NAFLD, SREBF1 was downregulated following induction of steatosis." (PMID 34988225, 2021). "Surprisingly, expression of Acaca was comparable between WT and Spp1−/− mice, while Srebf1, Fasn and Scd1 where even significantly downregulated in the Spp1−/− genotype, indicating that the increased steatosis observed in Spp1−/− mice cannot be explained by enhanced de novo lipogenesis (dnl)." (PMID 32281248, 2020).
steatosis (continued). "Accordingly, sleeve-gastrectomized rats exhibited a tendency towards a downregulation in hepatic Pparg (P = 0.084) and Srebf1 (P = 0.153) transcription factors as well as lower (P < 0.05) mRNA levels of Mogat2 and Dgat1 and mild steatosis evidenced by adipophilin staining." (PMID 28008992, 2016). "SREBF1 and FASN were included as indices of hepatic lipogenesis, as CVS activates the SREBF1-FASN axis and promotes steatosis." (PMID 41566055, 2026). "On the other hand, two genes (CYP1A2 and FMO1) were downregulated in hepatotoxicity pathway, two genes (SREBF1 and FASN) in steatosis, one each in necrosis (IPO4) and phospholipidosis (SLC2A3) pathways." (PMID 38992651, 2024). "ANGPTL8 reduced the steatosis (p < 0.05) and mRNA expression levels of PPARG2, SREBF1, MOGAT2 and DGAT1 lipogenic genes of palmitate-treated hepatocytes." (PMID 34884755, 2021). "The increase in steatosis, increased expression of CD36, SREBF1, and SCD1, and the decreased expression of CEACAM1 and GLUT2 are all key features also seen in our hyperglycemic HepG2 model as well as the Leprdb/J mouse model." (PMID 31805072, 2019). "Accompanying the observed steatosis, palmitic acid-induced lipid accumulation also leads to increased expression of CD36, SREBF1, and SCD1." (PMID 31805072, 2019). "We also investigated expression of sterol regulatory element binding transcription factor 1 (Srebf1) and fatty acids synthase (Fasn) as it has been reported that EPA can suppress hepatic lipogenesis and steatosis by reducing transcription of Srebf1." (PMID 27239345, 2016). "In addition to steatosis, paternal exposure to BPA led to a decrease in expression of Lepr, Igfbp2, and pAmpk, and upregulation of Srebf1 and Pparg in the liver of both male and female offspring." (PMID 39792613, 2025). "Of note, the steatosis observed in the KrO group is unlikely to be a consequence of increased de novo lipogenesis, because KrO significantly suppressed SREBF1 activity—the key regulator of hepatic lipid synthesis." (PMID 34444996, 2021). "Interestingly, ANGPTL8 inhibited steatosis and expression of lipogenic factors (PPARG2, SREBF1, MOGAT2 and DGAT1) in palmitate-treated human hepatocytes." (PMID 34884755, 2021). "Because TBE-31 decreased expression of Srebf1 and Xbp1s, we next explored whether TBE-31 antagonizes steatosis by suppressing ER stress." (PMID 29552625, 2018). "TIA1 nucleates SGs assembly and sequesters Srebf1 mRNA, leading to translational repression of the master lipogenic transcription factor SREBP1 and its downstream lipogenic program, thereby mitigating steatosis and subsequent inflammatory and fibrotic response." (PMID 41876477, 2026). "Moreover the lipogenic genes (SREBF1 and FADS1) found to be regulated in the present study are reported to be involved in steatosis but most of these studies are related to nutritionally induced steatosis." (PMID 25470483, 2014).
hepatocellular carcinoma (136 papers, 2012 to 2026). A malignant tumor that arises from hepatocytes. "In support, SREBF1 has been evidenced to potently inhibit fatty acid oxidation in hepatocellular carcinoma." (PMID 38369486, 2024). "SREBF1 has been shown to have a strong tumorigenic role in many malignant types including hepatocellular carcinoma, prostate cancer, and breast cancer." (PMID 37664030, 2023). "The Wikipathway gene set, SREBF and miR33 in cholesterol and lipid homeostasis, significantly overlapped with the genes containing high impact mutations in Tahpenes; studies have identified differential expression of the microRNA miR33 and pathways involving SREBF1 in human hepatocellular carcinoma." (PMID 35557512, 2022). "In hepatocellular carcinoma, PRMT5 has been linked to the increased half-life of SREBF1, an inducer of lipogenesis in the liver, which did not appear in the network analysis." (PMID 38132437, 2023).
breast cancer (132 papers, 2011 to 2026). A primary or metastatic malignant neoplasm involving the breast. "In vivo expression analysis in thyroid and breast cancer patients confirmed that lipid metabolism and SREBF1 expression are associated with increased metastatic potential and clinical aggressiveness." (PMID 41174748, 2025). "This SREBF1–breast-cancer brain metastasis association was also recovered in the MetMap500 dataset, indicating strong reproducibility of the finding." (PMID 33299191, 2020). "Previous studies have shown that as an important regulator of lipid metabolism, SREBF1 could promote tumor growth and metastasis of breast cancer, and was highly associated with EMT process." (PMID 37696831, 2023). "The tumorigenic function of the SREBF1 transcription factor, which was found to be overexpressed and positively associated with metastasis and poor prognosis in breast cancer patients, has been linked to oncogenic activation of the PI3K/AKT/mTOR signaling pathway." (PMID 34439480, 2021). "In breast cancer, high expression levels of SREBF1 are closely related to adverse outcomes and chemotherapy resistance, its specific mechanism is still not fully understood and requires further research." (PMID 40668814, 2025). "In this study, the mRNA expression levels of adipogenesis and lipogenesis-related markers, Pparg, Cebpa, Srebf1, Acaca, and Fasn in breast cancer subcutaneous adipose tissue were examined using RT-PCR." (PMID 40604704, 2025). "High expression levels of SREBF1 (gene encoding SREBP1) are correlated with poor recurrence-free survival (RFS) and distant metastasis-free survival (DMFS) in breast cancer patients." (PMID 40427160, 2025). "To determine the generality of the SREBF1 requirement for breast cancer growth in the brain, we knocked out SREBF1 in additional brain metastatic lines including HCC1954, MDAMB231 and HCC1806 using CRISPR–Cas9." (PMID 33299191, 2020). "Similarly, high expression levels of SREBF1 (gene encoding SREBP1) are correlated with poor recurrence-free survival (RFS) and distant metastasis-free survival (DMFS) in breast cancer patients." (PMID 40427160, 2025). "A study showed that the overexpression of ZSWIM3 (zinc-finger SWIM domain-containing protein 3) in MCF-7 cells promotes breast cancer progression and metastasis by enhancing the levels of SREBF1, SREBF2, and the levels of lipids, the effect that was reversed when ZSWIM3 was knocked out." (PMID 40427160, 2025). "O-GlcNAcylation of another transcription factor, SP1, increases sterol regulatory element-binding transcription factor 1 (SREBP1) expression and lipid synthesis in liver and breast cancer cells." (PMID 39178944, 2024). "Cancer cells are sensitive to sterols, and the expression of cholesterol and fatty acid biosynthesis genes (SREBF1/2, stearoyl-CoA desaturase (SCD), FASN) was inhibited by 25-HC in cancer cells, such as glioma, breast cancer, and prostate cancer cells." (PMID 36969840, 2023). "A significant inhibition of metastatic brain is observed in SREBF1 knockout breast cancer cell lines, demonstrating the importance of SREBP-1 in brain metastasis from breast cancers." (PMID 36009491, 2022). "Under pathological conditions, SREBF1 and FASN have been reported to be a pair of metabolically related oncogenes, which have been confirmed to be related to prostate cancer and breast cancer." (PMID 34799559, 2021). "Conversely, DMHCA increased expression of several LXR target genes, including SCD2, SREBF1, CPD and ABCA1, which positively correlate with increased survival in breast cancer subjects." (PMID 33780491, 2021). "One such pathway is SREBF1 (also known as SREBP1), which is hyperactivated upon Lats2 depletion in both mammary tumors (ingenuity activation z-score 0.64; P-value of overlap 3.6 × 10−8) and mouse livers." (PMID 30456386, 2018). "Moreover, SREBF1, a transcription factor that regulates lipid synthesis, promotes EMT in breast cancer cells." (PMID 37875594, 2023).
breast cancer (continued). "SREBF1 is a substrate for neddylation by the NEDD8-conjugating enzyme UBC12, and neddylation stabilizes SREBF1 with decreased ubiquitylation, contributing to the aggressive malignant phenotype of HCC and breast cancer." (PMID 36694250, 2023). "To explore this hypothesis, we analyzed the genome-wide occupancy of SREBF1 in three different cell types, namely SCC (TE5 and KYSE150 cell lines), liver cancer (HepG2 cell line) and breast cancer (MCF7 cell line)." (PMID 34272396, 2021). "SREBF1 was selectively required for growth of brain metastatic lines in culture compared with breast cancer lines with low or no brain metastatic potential." (PMID 33299191, 2020). "Knockdown of SREBF1 protein in breast cancer cells, however, did not block cell proliferation inhibition by LXR agonists." (PMID 25184494, 2014).
dyslipidemia (106 papers, 2009 to 2026). "This study has investigated the association between the transcription factors KLF14 and SREBF-1 and the promoters of orphan GPCRs, aiming to elucidate their potential role in metabolic syndrome." (PMID 40243421, 2025). "Computational analysis identified putative binding sites for KLF14 and SREBF-1 within the promoter regions of multiple GPCRs implicated in metabolic syndrome." (PMID 40243421, 2025). "Given that KLF14 and SREBF1 have been previously linked to metabolic syndrome, this observation suggests a direct connection between the regulation of these receptor expressions and the development of this condition." (PMID 40243421, 2025). "Collectively, these findings suggest a pivotal role of KLF14 and SREBF-1 in regulating the expression of a subset of GPCRs implicated in metabolic syndrome." (PMID 40243421, 2025). "Using the eukaryotic promoter database, we identified putative binding sites for the transcription factors KLF14 and SREBF-1 in the promoters of a panel of GPCRs associated with metabolic syndrome." (PMID 40243421, 2025). "Data also revealed a significant effect of SREBF-1 polymorphism, with a higher prevalence of metabolic syndrome and worse processing speed performance among G/G homozygous subjects, compared the A allele carriers." (PMID 30581395, 2018). "The data also point out possible effects of SREBF-1 polymorphism on both cognition and metabolic syndrome, highlighting the need to further explore putative converging mechanisms underlying both conditions." (PMID 30581395, 2018). "This study aims to determine the presence of the KLF14 and SREBF-1 transcription factor binding sites in the promoters of orphan receptor genes and to be able to associate some of these orphan receptors with the development of metabolic syndrome." (PMID 40243421, 2025). "In conclusion, this study provides strong evidence of the importance of KLF14 and SREBF-1 in regulating orphan receptors genes and their participation in the development of metabolic syndrome." (PMID 40243421, 2025). "All this represents a high probability of incidence of these receptors with the KLF14 and SREBF-1 TFs for their possible involvement in metabolic syndrome." (PMID 40243421, 2025). "The transcription factors KLF14 and SREBF-1 are key in metabolic syndrome due to regulating lipid and glucose metabolism genes." (PMID 40243421, 2025). "The network pharmacology studies showed that FASN, SCD1 (SCD) and SREBP1 (SREBF1) are targets for the treatment of postmenopausal dyslipidemia by TKRDF." (PMID 35872979, 2022). "This synthesis pathway with the use of sterol regulatory element-binding transcription factor 1 (SREBP-1c) is stimulated by high levels of insulin and cholesterol, which accompany the metabolic syndrome." (PMID 30959940, 2019). "We found that treatment with RBP can suppress HCHF diet-induced elevated expression of Srebf1 and Fasn with consequent alleviation of dyslipidemia." (PMID 26247962, 2015). "Methylation of SREBF1, although not in the matched CpG site of our study, affected BMI and was associated with glycemic traits, dyslipidemia, and coronary artery disease in a large set of adult cohorts." (PMID 41246799, 2026). "Additionally, the use of animal models is crucial to study the role of KLF14, SREBF-1, and orphan receptors in the development of metabolic syndrome in vivo." (PMID 40243421, 2025). "Collectively, these tissue expression patterns lend credence to the hypothesis that KLF14 and SREBF1 can regulate the expression of orphan receptors in tissues crucial for metabolic syndrome." (PMID 40243421, 2025). "While we observe an overlap in the expression of KLF14, SREBF1, and orphan receptors in tissues relevant to metabolic syndrome, specific expression patterns are also noted, which may have functional implications." (PMID 40243421, 2025).
dyslipidemia (continued). "First, our analysis of the tissue expression patterns of KLF14, SREBF1, and orphan receptors reveals a significant overlap in tissues relevant to metabolic syndrome, suggesting a potential functional interaction between these transcription factors and the receptors." (PMID 40243421, 2025). "This synthesis pathway using sterol regulatory element-binding transcription factor 1 (SREBP-1c) is stimulated by the high insulin and cholesterol levels that accompany the metabolic syndrome." (PMID 35566490, 2022). "No BS for either KLF14 or SREBF1 was identified in the promoters of MC4R, 5-HT2C, MC3R, S1PR2, FFAR1/GPR40, and HCR2 within this database, despite their known association with metabolic syndrome." (PMID 40243421, 2025).
diabetes (81 papers, 2008 to 2025). "Finally, the direction of association for CPT1A, ABCG1, SOCS3, TXNIP and SREBF1 was consistent with that reported in the literature for MetS and/or diabetes." (PMID 34780523, 2021). "SREBF1 (sterol regulatory element binding transcription factor 1), for which a significant association between methylation status and fasting glucose and 2-hour insulin was observed, has been linked to diabetes or related traits in human studies before." (PMID 27019061, 2016). "Thus, the overexpression of Srebf1 and Srebf2 has been shown to cause beta cell dysfunction and eventually diabetes, which at the cellular level is reflected by the repression of Pdx1 expression, impaired insulin secretion and content, as well as cellular triglyceride and cholesterol accumulation." (PMID 36232358, 2022). "GCG, IRS1, VEGFA, STAT3, CCL2, CASP3, and APOE as diabetes mellitus-related proteins and SREBF1, LPL, PPARA, APOB, GPT, MAPK8, and FASN as NAFLD-specific proteins were identified as possible discriminating factors between the two studied diseases." (PMID 35154608, 2021). "Diabetes significantly increases the mRNA expression of ACCα, HMGCR, and Srebf1, while RE significantly reduces the mRNA expression of these genes in the skeletal muscle of T2DM-RE mice compared to T2DM-SED mice." (PMID 39596482, 2024). "A comprehensive transcriptomic analysis involving type 2 diabetes mellitus patients further revealed that miR-124-3p and miR-16-5p affect the expression of genes such as CREB1, SP1, (both TFs in our analysis) SREBF1, and JUN (hub genes)." (PMID 36232337, 2022). "Dyslipidaemia and diabetes are closely related, and epigenome-wide approaches have identified differential methylation of genes known to have a key role in lipid metabolism and lipid traits, particularly CPT1A, ABCG1, SREBF1." (PMID 39827095, 2025).